TNF (tumor necrosis factor)
Diseases named in the same sentence as TNF in open-access papers (continued):
Sharing a sentence is not in itself a finding about the gene and the disease.
parasitemia (continued). "Mice lacking TNF receptors 1 and 2, the receptors for TNFα and LTα, had a higher peak parasitemia, reduced parasite killing in infected red blood cells (iRBCs), and delayed parasite clearance compared to control mice." (PMID 39452729, 2024). "This study measured C-reactive protein, IL-4, and TNF-α levels to determine the inflammatory status of patients who showed elevated levels of C-reactive protein and TNF-α in diabetic patients with or without parasite infections." (PMID 39199338, 2024). "Patients with detectable parasitemia measured by RT-PCR in peripheral blood had a higher concentration of TNF-α, IL-1β, IL-4, and IL-6, whereas those with negative RT-PCR showed elevated levels of IL-17A." (PMID 38133693, 2023). "In T. cruzi-infected nonpregnant women, IL-12p70 IL-15, IFN-γ, and TNF-α levels were positively correlated with parasitemia, whereas IL-10 was not." (PMID 38133693, 2023). "Also, parasite infection drives astrocytes to a pro-inflammatory profile with enhanced IL-6 and TNF-α production and TNFR1 expression, potentially favoring TNF signaling." (PMID 36439149, 2022). "BALB/c mice that were treated with anti-IFN-γ, anti-TNF, or both of these anti-cytokine antibodies had higher peak parasitemias than the mice treated with rat Ig, while depletion of IFN-γ or both IFN-γ and TNF impacted survival, with 3/5 and 4/5 mice succumbing to infection, respectively." (PMID 34663097, 2021). "The concentrations of TNF-α, proinflammatory cytokines, are expected to be increased in infection; however, its concentrations were significantly increased in children with RAP than that with parasitic infection." (PMID 34539633, 2021). "In Group C, there was a significant decrease in parasitemia and cytoadhesion in the placenta, a decrease in TNFα, and no decrease in birth weight." (PMID 34822508, 2021). "The production of pro-inflammatory cytokines (TNF-α, IL-1β, IL-6, and IFN-γ) in serum and brain homogenate of the vehicle-treated infected mice was significantly increased compared to the normal group on the peak day of parasitemia." (PMID 34975479, 2021). "In T. cruzi infection, treatment of IL-10–deficient mice with anti–IL-12 monoclonal antibody increased parasitemia, showing that IL-12, together with IFN-γ and TNF produced by innate immune cells, plays a pivotal role in controlling the parasitemia in early stages of infection." (PMID 34381739, 2021). "Besides clearing parasitemia, this treatment also resulted in a lower pulmonary mRNA expression of the inflammatory chemokines CCL2 and CXCL10, and of the cytokines tumor necrosis factor-α (TNF-α), IFN-γ, and IL-10." (PMID 33664739, 2020). "Furthermore, the immunization of SAG1-VLPs effectively decreased the production of specific cytokines, such as IL-1β, IL-6, TNF-α, and IFN-γ, after parasite infection." (PMID 32325746, 2020). "Therefore, the MAPK pathway plays a key role in the control of intracellular parasite infection, resulting in the regulation of inflammatory cytokines that are responsible for Th1 immune responses, including IFN-α/γ and TNF-α." (PMID 30740096, 2019). "The findings showed that major alterations occurred only at the acute parasitemia peak period (corresponding to 9 dpi) due to increased levels of IFN-gamma (5500-fold), TNF-alpha (754-fold) and IL-6 (260,000-fold) in untreated and infected mice as compared to uninfected and untreated animals." (PMID 30186314, 2018). "The delayed parasitemia patency coupled with prolonged parasitemia suppression and survival time in the treatment groups may be due to the high IFN-γ and TNF-α levels present prior to challenge infection." (PMID 28883981, 2017). "In this vein, TNF may promote parasite infection and growth as well as augment the expression of TNFR1 and, consequently, TNF/TNFR1 signaling, fueling NO production, which may also involve the NF-κB pathway." (PMID 27161638, 2016).
parasitemia (continued). "In these studies, IL-1β, IL-6, and TNF were upregulated more frequently in subjects with higher parasitemias and higher temperatures (data not shown)." (PMID 26491700, 2015). "Etanercept treatment statistically delayed mortality without altering the levels of parasitemia, revealing the critical role of TNF in the course of OI infection." (PMID 26090667, 2015). "We show that the parasitemia was higher at the early stage, i.e. at days 6–7 of Plasmodium berghei ANKA infection in Ly49E KO mice, which correlated with lower induction of CD69, IFN-γ and TNF-α in DX5− liver NK cells at day 5 post-infection." (PMID 24498110, 2014). "Although the dose used was previously shown to reduce LPS induced TNF-α production and we showed that high doses of melanin delayed increases in parasitemia and improved clinical scores, melanin treatment was not sufficient to increase survival in CM." (PMID 22242171, 2012). "Co-administration of mAb 2H8, a mouse mAb that binds to human FcαRI blocking the human IgA binding site, at the time of IgA delivery, failed to dramatically alter the course of parasitemia or the development of TNF-α responses (not shown)." (PMID 21781305, 2011). "JG single infected mice presented reduced parasitemia and heart parasitism, no mortality, levels of pro-inflammatory mediators (TNF-α, CCL2, IL-6 and IFN-γ) similar to those found among naïve animals and no clinical manifestations of disease." (PMID 20967289, 2010). "However, although Tip-DCs and TNF levels were reduced in CCR2 KO mice, control of parasitemia was unaffected." (PMID 20714353, 2010). "In murine models, the control of parasitemia is mostly mediated in the liver by IFN-γ- and MyD88-dependent generation of classically activated monocytic cells (M1) that secrete trypanotoxic molecules TNF and NO and exert phagocytic activity." (PMID 20714353, 2010). "Although TNF and IFN-γ are involved in the control of parasitemia during T. brucei infection, parasitemia in WT and CCR2 KO mice was similar indicating that reduced production of TNF and IFN-γ in CCR2 KO mice was still sufficient for efficient parasite control (not shown)." (PMID 20714353, 2010). "TNF, a pro-inflammatory cytokine produced primarily by γδ T cells and CD14+ monocytes during malaria infection in humans, plays a key role in controlling parasitemia, but can cause damage if not tightly regulated." (PMID 41279035, 2025). "However, one study did not see a clear increase of TNF and IL-6 in asymptomatic parasitemia but, as expected, observed higher levels of TNF and IL-6 in individuals with acute malaria compared to those with asymptomatic infection." (PMID 40933276, 2025). "Parasitic infections often lead to the upregulation of many inflammatory mediators, including Th1 cytokines (interleukin (IL)-1β), Th2 cytokines (IL-5, IL-6 or IL-10), Th17 cytokines (IL-17), cyclooxygenase-2 (COX-2), tumor necrosis factor-α (TNF-α), and nuclear factor (NF)-κB." (PMID 40181380, 2025). "Thus, lack of activation of macrophages by IFNγ did impact parasitemia in a limited way, but compensatory mechanisms, potentially through TNFα, led to clearance of the parasite." (PMID 39452729, 2024). "Neutralizing TNF prevents most of the symptoms in this model of hyperinflammatory experimental cerebral malaria, including gliosis, increased levels of fibrin(ogen) in the brain, behavioral changes, and mortality, without affecting parasitemia." (PMID 38115011, 2023). "TNF-α can inhibit tumor cell proliferation, induce tumor cell apoptosis, participate in the immune regulation of the body, and induce the expression of related cytokines and their receptor genes in mammals; TNF-α plays an important role in resisting bacterial, viral, and parasitic infections." (PMID 36670802, 2023).
parasitemia (continued). "In the early stage of a parasitic infection, the levels of host CD4+ and CD8+ T cells are increased, and Th1 or Th17 immune response is the mainstay, which exerts anti-parasitic effects by secreting interferon-γ (IFN-γ), tumor necrosis factor-α (TNF-α), or interleukin-17 (IL-17)." (PMID 36466695, 2022). "In contrast, the TNF plasma levels were not affected by pre-exposure to the DTPa vaccine and were infection driven, being identical in both the non-vaccinated and DTPa-vaccinated mice at the timepoint of peak parasitemia (Tp)." (PMID 34200074, 2021). "Unlike most parasitic infections, such as helminth, which rely on eosinophils, P. falciparum is capable of suppressing eosinophilia, and is characterized by secretion of Th1 cytokines IFNγ and TNF." (PMID 32033605, 2020). "The lack of IL-1β and TNF-α, both typically elevated in malarial disease, may also be due to downregulation by IL-10, which increases with rising parasitemia." (PMID 32958528, 2020). "At peak parasitemia, there was a significant increase in TNF/IL-10 coproduction in response to in vitro pRBC restimulation (P = .04), with no significant changes in single TNF or IL-10 production." (PMID 30239833, 2019). "Thus, balance between these 3 cytokines; IFN-γ, TNF-α, and IL-10 levels are critical for moderating parasitic disease severity, and establishment of long-term, non-fatal diseases." (PMID 30619263, 2018). "In this work, Nod1−/− mice were shown to be very susceptible to T. cruzi, succumbing to the infection and displaying higher parasitemia and parasite loads in the spleen and heart tissues, although NOD1 deficiency does not impair the production of different cytokines as IL-12, TNF-α, IFN-γ, or IL-10." (PMID 22496959, 2012). "It was confirmed that cytokines such as IL-12, TNF-α, IFN-γ, and IL-2 play an important role in controlling the proliferation of Babesia in the early and acute stages of infection, while IL-10, IL-4, IL-5, and IL-6 may involve in chronic and low parasitemia stages of infections." (PMID 32733477, 2020). "In mothers of noninfected children, parasitemia showed a positive correlation with the levels of IL-12p70, IL-15, IFN-γ, and TNF-α and a negative correlation with IL-6." (PMID 38133693, 2023). "Serum concentration of IL-1α, IL-1β, IFNγ, CXCL10, CXCL9, TNFα in non-infected mice and mice infected with either 1/148 or IL3000, at the first peak of parasitemia (Mean ± SEM; N=3–4)." (PMID 35787830, 2022). "TNF is produced by NK cells, CD4+ T cells, macrophages, monocytes, and neutrophils, and although there were higher parasitemias in mice depleted of TNF, this did not affect the survival of vaccinated mice." (PMID 34663097, 2021). "An animal study on dogs evaluating relationship of PCT with different inflammatory biomarkers (TNF-α, IL-1β, IL-6, and IFN-γ) produced during viral, bacterial, and parasitic infections showed that PCT showed a weak significant negative correlation with IFN-ꝩ levels in serum." (PMID 39343776, 2024). "Neither TNF nor IFN-γ concentrations were changed in the hippocampi or sera of mice in the two infected groups, suggesting that the change in parasitemia is not downstream of systemic cytokine levels." (PMID 38115011, 2023). "However, the interesting results were the significant higher concentrations of pro-inflammatory TNF-α- and lower concentrations of anti-inflammatory IL-10- cytokine in the RAP children without organic disease compared to children with parasitic infections." (PMID 34539633, 2021). "In vivo injection of anti-FasL, but not anti-TNF-alpha or anti-TRAIL antibodies, blocked activation-induced cell death of CD8+ T cells, improved type 1 immune responses, and reduced the infection severity as estimated by parasitemia." (PMID 28536576, 2017).
parasitemia (continued). "iRBC- and TLR1/2 and TLR4 agonist-induced CD86 expression was also lower in CD1c+ cells isolated at peak parasitemia than prior to infection, while there was no change in TLR1/2 and TLR4-induced IL-12 expression and all three stimuli, iRBCs, TLR1/2 and TLR4 agonists, increased intracellular TNF." (PMID 31900030, 2020). "Treatment with anti-FasL mAb starting at 11 days after infection, but not anti-TNF or anti-TRAIL antibodies, protect CD8 T cells from AICD, improved cytokine production by CD4 T cells, activate CD8 T cells, upregulate Fas expression by CD8 T cells earlier than CD4 T cells, and decreased parasitemia." (PMID 28536576, 2017).
chronic kidney disease (242 papers, 2010 to 2026). Impairment of the renal function secondary to chronic kidney damage persisting for three or more months. "In patients receiving anti-TNF therapy, chronic kidney disease also emerges as a significant contributor to increased risk." (PMID 40700294, 2025). "Usually, end-stage renal disease is linked to a variety of changes in the immune system and both anti-inflammatory interleukin (IL-10) and proinflammatory cytokines (TNF-, IL-6) are elevated." (PMID 38206949, 2024). "In the presence of amyloidosis with intervenient infections, the risk of chronic renal failure can be kept in mind even if the patient is receiving TNF inhibitors." (PMID 39229360, 2024). "Trimethylamine-N-oxide (TMAO) is a gut microbiota-derived metabolite and TNF-α is proinflammatory cytokine, both known to be associated with renal inflammation, fibrosis and chronic kidney disease." (PMID 38643262, 2024). "The study found that neutrophils in patients with chronic renal failure were significantly higher than those in healthy people, and were associated with IL-6 and TNF-α." (PMID 38152332, 2023). "Specifically, several markers of inflammation, including interleukin-6 (IL-6) and tumor necrosis factor-α (TNFα), have been particularly implicated in the progression of chronic kidney disease." (PMID 37033595, 2023). "Neutralizing inflammatory cytokines (TNF) can reduce the level of FGF23 in animal models of chronic kidney disease (CKD) and high levels of FGF23 are associated with increased cardiovascular morbidity and mortality in patients with CKD." (PMID 35370667, 2022). "Activation of the tumor necrosis factor-α pathways is associated with renal function decline in patients with chronic kidney disease." (PMID 35413081, 2022). "In a chronic renal insufficiency cohort study, inflammation markers (IL-1β, IL-1 receptor antagonist, IL-6, TNF-α, hs-CRP, and fibrinogen) were associated with decreased kidney function." (PMID 35628912, 2022). "The TNF-α observation is at odds with those in the Chronic Renal Insufficiency Cohort Study where plasma TNF-α was associated with a rapid reduction in kidney function." (PMID 33327377, 2020). "Apart from adiponectin, TNF-α has also been associated with the development of renal dysfunction and chronic kidney disease." (PMID 29636702, 2018). "Numerous studies have reported an association between markers of inflammation like CRP, IL-6, TNF-α and fibrinogen and chronic kidney disease (CKD)." (PMID 28494192, 2017). "Less prominent risk factors were immunosuppressive treatments, TNF-antagonists therapy, chronic renal failure and HIV infection." (PMID 27866367, 2017). "Patients with human immunodeficiency virus (HIV), vitamin D deficiency, silicosis, end stage renal disease, diabetics, smokers, alcoholics, and patients on TNF antagonist therapy or corticosteroids are all at increased risk." (PMID 27895668, 2016). "Therapies with ACE inhibitors in patients with congestive heart failure or advanced chronic renal disease have demonstrated that is associated with a significant decrease in TNF-α and IL-6 activity." (PMID 25785280, 2015). "Elevated levels of interleukin-6 and tumor necrosis factor-alpha in the circulation are associated with vascular calcification in patients with chronic kidney disease." (PMID 23199021, 2012). "Elevated levels of pro-inflammatory cytokines, such as interleukin-6 and tumor necrosis factor-alpha, have been consistently implicated in the pathogenesis and progression of chronic kidney disease, contributing to renal inflammation, fibrosis, and accelerated decline in glomerular filtration rate." (PMID 41602165, 2026). "Several biomarkers of inflammation including IL-6, IL-1β, IL-1 receptor antagonist, CRP, TNF-α, and fibrinogen were directly associated with albuminuria and inversely associated with the measures of kidney function in the Chronic Renal Insufficiency Cohort (CRIC) study." (PMID 37840653, 2023).